EPHA2 (EPH receptor A2)
Diseases named in the same sentence as EPHA2 in open-access papers (continued):
Sharing a sentence is not in itself a finding about the gene and the disease.
tumor (continued). "Moreover, as the depth of invasion increases and the tumor progresses into the submucosa, EphA2 is more likely to be released into the bloodstream." (PMID 39766211, 2024). "GC with EphA2 overexpression may show a greater possibility of invisible metastasis, distant metastasis, tumor invasion, worse clinical staging, recurrence, tumor differentiation, and poor prognosis." (PMID 39839790, 2024). "Importantly, cross reactivity with recombinant mouse EphA2 protein was also demonstrated (KD 3.82 ± 0.56 nM), allowing for the detection of any EphA2 mediated uptake in non-tumor tissue." (PMID 39239524, 2024). "IF analysis of mouse xenografts revealed that TGFBI inhibition decreased EphA2 levels in the tumor." (PMID 39346536, 2024). "A recent study reported that the FOSL2 transcription factor could drive the expression of oncogene EphA2 to induce cell proliferation, metastasis, and tumor progression in various tumors." (PMID 39010083, 2024). "The VM structure was more abundant after overexpression of EphA2 OE, while it was more difficult to find in EphA2 KD group, and the same phenomenon could be observed in the tumor internal vascular thermogram." (PMID 39050762, 2024). "In tumors, EphA2 overexpression is associated with noncanonical pathway activation, tumor progression, and a poor prognosis, which has emphasized its importance as a marker of malignancy." (PMID 39596256, 2024). "Our data also indicate that EphA2 significantly contributes to OS cell migration/invasion and tumor growth and reduces the sensitivity of OS cells to a commonly used chemotherapeutic drug, cisplatin, potentially through the activation of SRC, AKT and/or ERK–MAPK pathways." (PMID 39056783, 2024). "EphA2 expression was also assessed in four canine OS tumor samples by immunohistochemistry." (PMID 39056783, 2024). "In vitro experiments demonstrated that both CAR-T cells could be activated by EphA2-positive tumor cells, with EphA2-a CAR-T exhibiting significantly higher tumor-killing efficiency compared to EphA2-b CAR-T." (PMID 39506843, 2024). "In summary, most Eph receptors (EphA1, EphA2, EphA3, EphA4, EphA5, and EphA7) function as promoters of GC progression, influencing metastasis, tumor invasion, angiogenesis, and drug resistance, while EphA1 has a more complex role depending on tumor differentiation." (PMID 39839790, 2024). "It is frequently overexpressed in malignant cells and has been suggested to be an important factor in tumour growth, survival, metastatic processes, and angiogenesis Our findings add to the body of evidence suggesting the influence of EphA2 on tumour response to dasatinib." (PMID 38369747, 2024). "Further modifications of BCY18469 to increase even more its affinity towards EphA2 or its contact surface area with the receptor, could potentially improve the tumor retention over time." (PMID 39239524, 2024). "Furthermore, a significant correlation was observed between EphA2 expression and the pathological stage of this tumor, with high EphA2 expression being correlated with a poor prognosis." (PMID 39839790, 2024). "In vivo PET/MR and SPECT/CT imaging studies were performed using [68Ga]Ga-BCY18469 and [111In]In-BCY18469, respectively, along with biodistribution of [177Lu]Lu-BCY18469 up to 24 h post injection in HT1080- and PC-3-tumor bearing BALB/c nu/nu EphA2-overexpressing xenograft mouse models." (PMID 39239524, 2024). "And knockdown of EPHA2 expression reversed the pro-tumour effects of USP3-upregulating." (PMID 38531846, 2024). "In addition, we found genes associated with tumor progression were downregulated; among these were heat shock proteins (HSP), such as HSPH1, HSPD1, LYAR and EPHA2." (PMID 38992681, 2024). "However, as an inhibitor of VM in gallbladder cancer, norcantharidin can block the EphA2/FAK/paxillin signaling pathway to inhibit tumor VM formation." (PMID 37175948, 2023). "Inhibition of EPHA2 suppresses tumor initiation and progression, enhancing OS." (PMID 37444544, 2023).
tumor (continued). "Inhibition of EphA2 by inhibitors, conjugated peptides or agonistic antibody is sufficient to induce tumor cell death and inhibit tumor growth; however, several studies have also identified EphA2 as tumor suppressor." (PMID 37816703, 2023). "The downregulation of amphiregulin, IL-6 and EPHA2 suggests interference with pathways critical for tumor growth and progression and may explain the pronounced effect seen in the in vivo study." (PMID 37803074, 2023). "Furthermore, the reversal of the promoting effect on HBV replication and tumor cell growth by the miR-520e inhibitor was achieved through the utilization of si-ephA2." (PMID 37444544, 2023). "Whether EphA2, an important receptor tyrosine kinase, can promote tumor development through the occurrence of phase separation has not been reported." (PMID 37980165, 2023). "Mice lacking EphA2 were shown to be more susceptible to chemically induced skin carcinogenesis, leading to increased tumour growth and invasion." (PMID 36830852, 2023). "EPHA2 was upregulated in tumour compared with histologically normal tissue surrounding it." (PMID 36890818, 2023). "EphA2 is a protein tyrosine kinase that requires ephrin-A1 binding for its phosphorylation and activity; although EphA2 is usually activated by binding with ephrin-A1, it has been reported that in some highly aggressive tumor cells, EphA2 can be constitutively active." (PMID 37298296, 2023). "Therefore, EphA2 is closely involved in the processes involved in the transition from tumor carcinogenesis to malignant progression, suggesting a potential therapeutic target for cancer." (PMID 37712876, 2023). "Ephrin receptors and ligands also play important roles in KSHV pathogenesis; EphA2 and EphA4 receptors and Ephrin-B2 ligands are abundantly expressed in KS cell lines and tumor biopsies, and Ephrin-B2 acts as an essential factor in KS cell viability and tumor growth." (PMID 36656913, 2023). "EphA2 is highly expressed in many tumours and is of prognostic importance." (PMID 37980165, 2023). "Furthermore, ECs downregulate Slit2, a tumor-suppressive angiocrine factor inhibited by EphA2, thereby facilitating tumor proliferation and motility." (PMID 37666809, 2023). "Moreover, elevated Eph receptor expression has been detected in the tumour microenvironment, as well as in tumour cells, including during tumour neo-angiogenesis, as exemplified by the role of EphA2 in endothelial cell migration and tumour vessel assembly." (PMID 37760615, 2023). "Likewise, EphA2 has been proposed as a tumor suppressor, which is upregulated at transcript and protein levels in human tissue samples and cancer cell lines." (PMID 37880732, 2023). "Only 30% of patients with GBM harbor the EGFRvIII mutation, but fortunately, EphA2 and IL13Ra2 are not expressed in normal brain tissue, making it sufficient to target a CNS-specific and not necessarily a tumor-specific antigen." (PMID 37754534, 2023). "In conclusion, EPHA2 plays a crucial role in HCC tumor growth." (PMID 37444544, 2023). "In particular, EphA2, EphA3, EphA4, and EphB4 are promising therapeutic candidates, based on increased expression in tumours and the TME, and drugs targeting these receptors have shown some promise in tumour models, with mixed success in the limited clinical studies performed to date." (PMID 36830852, 2023). "Furthermore, the tumor-suppressive function of EphA2 was significantly exhibited in patients with the HER2-negative luminal A subtype." (PMID 37816703, 2023). "EPHA2 was observed in most epithelial cells from normal or tumor tissues." (PMID 38008720, 2023). "The study used CRISPR-Cas9-mediated inhibition of EPHA2 expression in the mouse liver and showed a significant reduction in tumor burden compared to the control, indicating that EPHA2 may be a potential therapeutic target for HCC." (PMID 37444544, 2023).
tumor (continued). "Irradiation with 5 Gy enhanced tumor cell migration of NSCLC NCI-H358 cells in dependence of EphA2." (PMID 36998455, 2023). "In vivo studies carried out on groups of 4-week-old athymic nude mice that were induced with subcutaneous TNBC, showed that the localized release of the EphA2-conjugated drugs was effective in complete elimination of residual tumor after local surgical resection." (PMID 37530973, 2023). "SHC binds with EPHA2, which is known to regulate tumor growth, migration, and invasiveness." (PMID 35342659, 2022). "In in vitro and in vivo models, EphA2 contributes to tumor growth and VM formation." (PMID 36418859, 2022). "Furthermore, the combination of pazopanib and trametinib targets PI3K/Akt and MEK/ERK pathways, inhibiting tumor growth through a decreased expression of EPHA2." (PMID 36077137, 2022). "These preliminary data suggest thattargefrin is well tolerated and that it could selectively deliverPTX to EphA2-expressing tumor cells." (PMID 36331527, 2022). "Given the diversity and complexity of cell signaling pathways, there may be multiple EphA2-related signaling pathways in tumor cells, which together play a role in promoting cancer." (PMID 36478746, 2022). "Notably, GRN KO cells generated tumors with significantly higher tumor volume as compared to both parental and EphA2 KO MSTO-211H cells." (PMID 36471440, 2022). "We also link EPHA2 overexpression with tumor proliferative capacity (Ki-67 LI)." (PMID 35204461, 2022). "Thus, exosome‐mediated EphA2 expression in cancer cells plays an essential part in tumor drug resistance." (PMID 35587712, 2022). "Due to EphA2 overexpression in many types of cancers, as explained in Section 3, the process of ligand induced receptor endocytosis and the consequent degradation have been widely analyzed as potential routes to reduce tumor malignancy." (PMID 36142306, 2022). "However, activation of EphA2 is known to exhibit tumor-suppressive activities; thus, the exact mechanism of tumor-promoting activity of EphA2 was unclear." (PMID 36132127, 2022). "However, the expression and function of EPHA2 on tumor cell-derived exosomes have received little attention." (PMID 35673569, 2022). "Neutral liposomes loading siRNA to silence EPHA2 and to inhibit tumour cells growth." (PMID 36295976, 2022). "We speculate that the targeting EphA2 and PD-L1 may produce more significant tumor suppression than monotherapy." (PMID 36478746, 2022). "Finally, we compared the ability of parental, GRN or EphA2 KO MSTO-211H cells to modulate in vivo tumor formation." (PMID 36471440, 2022). "High expression of EPHA2 is an indicator of high tumor cell aggressiveness." (PMID 35673569, 2022). "The measurement data showed that knockdown of EphA2 significantly inhibited tumor growth." (PMID 36478746, 2022). "γδ T cells play increasing tumor-killing ability by recognizing EphA2." (PMID 35603176, 2022). "Interestingly, anchorage-independent growth, migration, and xenograft tumor growth were increased when either EGFR or EphA2 was overexpressed, but these effects were dependent on the presence of Ephexin1." (PMID 35668076, 2022). "Furthermore, the binding of EGFR and EphA2 to each other correlates to Ephexin1 levels, and interactions between EGFR and EphA2 are associated with an increasingly poor tumor tissue grade." (PMID 35668076, 2022). "More importantly, EPHA2 showed a positive correlation with LRRC8A in most studies of PAAD, and its knockdown resulted in a decrease in EPHA2 expression, which was demonstrated to be involved in anti-tumor immunity by regulating prostaglandin-endoperoxide synthase." (PMID 36428619, 2022). "The survival of tumor-bearing mice after EphA2 CAR-T cell treatment was significantly improved." (PMID 35920986, 2022). "An interesting crosstalk has been described between the PI3K/Akt pathway and EphA2 in tumor cells." (PMID 34440844, 2021).
tumor (continued). "In addition, EphA2-targeted CAR-T cells remarkedly reduced or eliminated tumor burden in a mouse model of disseminated OS metastasis." (PMID 34503279, 2021). "Mouse studies indicate that the loss of EphA2 is not essential for primary PDAC tumor development, but it is required for metastasis." (PMID 33891893, 2021). "Importantly, deletion of EphA2-SE was shown to suppress cell proliferation, invasion, migration and tumor progression by blocking PI3K/Akt and WNT/β-catenin signaling pathway." (PMID 33712565, 2021). "The positive correlation between high PD‐L1 and EphA2 in our study may indicate that EphA2 expressing tumor parts are immune‐suppressed but further analyses are required to prove such a statement given the small sample cohort analyzed." (PMID 33768639, 2021). "Indeed, both in our bioinformatic investigation and in our qRT-PCR analysis of primary tumor and surrounding normal tissues, we demonstrated a significant differential expression of EPHA2 (higher expression in pathological tumor tissue vs. healthy tissues)." (PMID 34831119, 2021). "However, it was later shown that tumour cells are able to form and maintain blood vessels by expressing neuropilin-2, EphA2, and laminin-15γ2." (PMID 34638234, 2021). "Finally, a combined expression of EphA2, EphA3, EphB2 and IL-13RA2 is observed in almost every GB patient, presenting in tumor-infiltrating cells, tumor-initiating cells or GSCs and neovasculature." (PMID 34209513, 2021). "However, in addition to pro-oncogenic functions of EphA2, tumor suppressor functions were likewise described." (PMID 33572758, 2021). "EphA2 expression is highly correlated with the tumor-propagating potential of GBM cells with stem-like properties while elevated levels of EphA3 help to maintain tumorigenicity in tumor-initiating cells." (PMID 33673213, 2021). "In addition, the fact that EphA2 KD in MDA‐MB‐231 tumor cells phenocopies expression of the dominant negative mutant capable of mediating reverse signaling in 4T1 tumor cells also provides support for this model." (PMID 33869989, 2021). "In xenograft mouse model, COE inhibited tumor growth and VM formation via down-regulating EphA2." (PMID 33867982, 2021). "In absence of E-cadherin, associated with reduced cell-cell contacts and pro-metastatic behavior of the cancer cells, EphA2 was redistributed to membrane ruffles where it cannot engage with membrane-bound ligand ephrin-A1 on adjacent cells, thus reducing the tumor-suppressive juxtacrine signaling." (PMID 33572284, 2021). "Importantly, we found that blocking of EphA2 expression significantly inhibits cytotoxicity of tumor reactive Vδ1 γδ T cells." (PMID 34691070, 2021). "We found that the knock‐down of EphA2 significantly decreased CC tumour development." (PMID 33586348, 2021). "This analysis revealed high levels of EphA2 protein expression in tumor cells (arrows)." (PMID 33869989, 2021). "For the AsPC-1 mouse tumour cells, EPHA2 appears to be similarly expressed between 2D and 3D." (PMID 34552183, 2021). "The most well-characterised example of this is for EphA2, where the classical ligand- and tyrosine kinase-dependent signalling mechanism is accompanied by a pathway in which tumour promotion is achieved independently of ligand or tyrosine kinase activation of the receptor." (PMID 33430066, 2021). "The binding of Vav2 to EphA2 is crucial for EphA2-mediated tumor angiogenesis." (PMID 34068055, 2021). "In tumor endothelial cells, EphA2 canonical signaling promotes tumor angiogenesis." (PMID 34857764, 2021). "However, an oHSV engineered to express the C57BL/6 EphA2 antigen improved survival and memory response suppressing tumor growth on rechallenge in survivors or induced CD8 cells with improved antigen response." (PMID 34599026, 2021).
tumor (continued). "The analyses revealed a significantly (p < 0.01) higher EPHA2 expression in tumor samples compared to normal tissue and, in two datasets (GSE34620, GSE63155), a significant (p = 0.001 and p = 0.042, respectively) gene upregulation in tumors from male compared to female subjects." (PMID 34831119, 2021). "In addition, clinical pathological analysis revealed that the overexpression of EphA2 in CC tissue specimen was positively correlated with the tumour stage and lymph node metastasis." (PMID 33586348, 2021). "We found that EphA2 overexpression significantly increased tumour size and weight in NOD SCID mice." (PMID 33586348, 2021). "Other reports have demonstrated that both EphA and EphB receptors could influence tumor cell responses to IR including EphA2 in NSCLC." (PMID 33671073, 2021). "Thus, EphA2 is required to maintain pancreas tissue health by promoting the elimination of KrasG12D cells, with the retention of mutant cells accelerating tumor initiation." (PMID 33891893, 2021). "Finally, to confirm the inhibition of the EPHA2 resulting in significantly decreased in vitro tumor cell death, we generated EPHA2 knockouts (KO) in endometrial cell line RL95-2 by the CRISPR/Cas9 method." (PMID 34691070, 2021). "We demonstrated higher EPHA2 expression in tumor tissues when compared to normal counterparts." (PMID 34831119, 2021). "Another question raised by our results is whether this in vivo vaccination strategy applies to other shared tumor antigens or whether EphA2 is unique in its ability to stimulate this immune recognition after OV expression." (PMID 34599026, 2021). "Furthermore, dogs were used to test the performance of a nanotherapeutic encapsulating a hydrolytically sensitive Docetaxel prodrug and conjugated to an antibody specific for EphA2, demonstrating an improvement in tumor penetration and antitumor activity." (PMID 34631854, 2021). "The discrepancy between the protein and mRNA levels of EPHA2 may be due to the fact that high levels of EPHA2 in tumor cells are the result of increased protein stability." (PMID 33977106, 2021). "Knock‐down efficiency of EphA2 protein in the tumours was determined by Western blot analysis." (PMID 33586348, 2021). "Finally, data obtained from in vivo animal models verified that the simultaneous inhibition of EphA2 with sorafenib treatment can effectively overcome sorafenib resistance and extend the projected survival of resistant tumor-bearing mice." (PMID 32203105, 2020). "In line with our OVCAR and patient cell results, platinum treatment of TYK‐nu enhanced EphA2 (total and pS897) and reduced the tumor‐suppressive EphA2‐pY588, thus increasing pS897/pY588 ratio (5 μM cisplatin 8.6 ± 0.3, 10 μM cisplatin 8.0 ± 0.4‐fold increase, P ≤ 0.009)." (PMID 32115889, 2020). "Furthermore, several studies have reported that, under Akt activation, EphA2 phosphorylation at Ser897, which has been reported as a potential site regulated by Akt, drives tumor cells toward oncogenic survival and metastatic pathways." (PMID 32203105, 2020). "EPHA2 inhibition was validated to recover anti-tumor efficacy in Erlotinib-resistant tumors." (PMID 32933200, 2020). "Moreover, EphA2-Fc inhibited 4 T1 tumor growth in vivo and reduced tumor vascular density and growth while increasing cell apoptosis." (PMID 32811512, 2020). "Furthermore, soluble EphA2-Fc was demonstrated to inhibit endothelial cell migration upon 4 T1 mouse mammary adenocarcinoma tumor cell-induced angiogenesis in vitro." (PMID 32811512, 2020). "Moreover, there was a converse correlation between E-cadherin and EphA2 expressions in advanced tumor stages." (PMID 32795296, 2020). "Notwithstanding these results, the overexpression of EphA2 in many tumor types may yet provide a therapeutic window for other antibody-based approaches." (PMID 32397088, 2020).